NAPRT (nicotinate phosphoribosyltransferase)
Diseases named in the same sentence as NAPRT in open-access papers (continued):
Sharing a sentence is not in itself a finding about the gene and the disease.
cancer (continued). "The nicotinate phosphoribosyltransferase (NAPRT) gene has gained relevance in the research of cancer therapeutic strategies due to its main role as a NAD biosynthetic enzyme." (PMID 34946971, 2021). "For example, NAPRT is amplified and overexpressed in a subset of common types of cancer, including ovarian cancer, where its expression correlates with a BRCAness gene expression signature." (PMID 32477131, 2020). "The inhibition of NAMPT and NAPRT sensitizes cancer cells to DNA damage, such as DSB-inducing drugs or alkylating agents." (PMID 32722390, 2020). "For example, it has been shown that in cancer cells that lack NAPRT expression and in which NAD synthesis solely depends on NAMPT, NAMPT inhibitors are significantly more potent." (PMID 32477131, 2020). "Cancers arising from tissue with a highly NAPRT are expression completely and irreversibly dependent on the NAPRT-regulated de novo pathway, while cancers deriving from tissues with the low level of NAPRT mainly rely on the NAMPT-mediated NAD+ salvage pathway." (PMID 33028824, 2020). "NAPRT gene amplification in tumors correlated with NAPRT expression in matched normal tissues, suggesting a role for tissue context in determining which cancers amplify NAPRT." (PMID 32266141, 2020). "Our present study detected NAMPT and NAPRT protein expression in cancer and adjacent tissues from 261 CRC using immunohistochemical staining." (PMID 31448236, 2019). "In conclusion, we first investigated the clinicopathological and prognostic value of NAMPT and NAPRT in cancer and adjacent tissues from 261 CRC patients." (PMID 31448236, 2019). "For example, IDH mutant cancers have been shown to have exquisite sensitivity to NAMPT inhibitors, as have tumors deficient in NAPRT." (PMID 32010616, 2019). "As observed in these tissue slices and cancer cell lines, NAPRT stains strongly in the nucleus but is also present in the cytoplasm of cells." (PMID 29100430, 2017). "All levels of positive staining (+, ++ or +++) were considered positive based on the fact that low level NAPRT expression in cancer cell lines is sufficient to rescue cell death from NAMPTi inhibition with niacin." (PMID 29100430, 2017). "In this study, we demonstrated cell-specific metabolic responses to FK866 treatment at 50 and 5 nM concentrations for 24 hours and ability to recuperate with nicotinic acid treatment for human cancer cells having NAPRT pathway available." (PMID 25486521, 2014). "Additionally, cancer cell lines with low expression of NAPRT allowed for high dose treatment of FK866 and in vivo rescue of xenografted mice with nicotinic acid, the precursor to NAD biosynthesis via NAPRT, without sacrificing the therapeutic potential." (PMID 40526635, 2025). "In these instances, administering NAMPT inhibitors in combination with NA is postulated to help many healthy, NAPRT-proficient tissues, but not NAPRT-deficient cancer cells in avoiding the consequences of NAMPT obstruction." (PMID 38396769, 2024). "To test the first hypothesis, we examined whether certain NAPRT-positive cancer cell lines sensitive to FK866 are subjected to NAM-competitive NAMPT inhibition and NAD+ depletion by FK866." (PMID 37771778, 2023). "Regardless of the cancer type, NAPRT-deficient cancer cell lines were more susceptible to A4276 than the NAPRT-positive cancer cell lines." (PMID 37771778, 2023). "Notably, cancers arising from normal tissues with high levels of NAPRT have a high frequency of NAPRT gene amplification and their survival fully depends on NAPRT." (PMID 36770640, 2023).
cancer (continued). "The NAPRT gene is frequently amplified and overexpressed in several types of tumors, including ovarian, pancreatic, liver, and colorectal cancers, which is in keeping with the higher demand of cancer cells for NAD+ compared to normal cells." (PMID 36770640, 2023). "FK866 is a tight-binding, competitive inhibitor of NAMPT 29; therefore, we compared A4276 with FK866 to gain insights into the mechanism underlying A4276's superior selectivity against NAPRT-negative cancer cell lines." (PMID 37771778, 2023). "Moreover, in NAPRT- and NAMPT-dependent cancers where the related enzyme is deficient, an alternative route for producing NAD+ via NRK1 is activated." (PMID 37175631, 2023). "Altogether, these findings suggest that the inhibition of NAPRT activity might be of therapeutic potential in cancer treatment." (PMID 36770640, 2023). "Both in vitro and In vivo comparative analyses were conducted between A4276 and other NAMPT inhibitors to evaluate the NAPRT-negative cancer cell selectivity and the underlying distinct NAMPT inhibition mechanism of A4276." (PMID 37771778, 2023). "Therefore, in cancers with low-NAPRT expression, inhibition of NAMPT is a potential therapeutic approach." (PMID 37771778, 2023). "The specific cytotoxicity of A4276 sparing NAPRT-positive cell lines in multiple cancer types and normal cells led us to propose three hypotheses regarding the nature of NAMPT inhibitors." (PMID 37771778, 2023). "The key enzymes of NAD+, such as de novo synthesis-nicotinate phosphoribosyltransferase and salvage synthesis-nicotinamide phosphoribosyl-transferase, are overexpressed in various cancers and contribute to higher glycolytic activity, cancer progression, chemoresistance, and poor prognosis." (PMID 35855334, 2022). "We recently showed that inhibiting NAPRT could prove useful for sensitizing several cancer cells to NAMPT inhibitors." (PMID 35396381, 2022). "According to this approach, NAPRT expression within tumor cells is the key determinant of the cancer types that might benefit from it." (PMID 34068917, 2021). "A recent study reported overexpression of the NAPRT gene in a subset of common types of cancer such as breast, prostate, liver, pancreatic, ovarian, and head and neck cancers, where it promotes cancer cell metabolism and reduces the susceptibility to NAMPT inhibitors and DNA-damaging drugs." (PMID 33609766, 2021). "In addition to cancer, the role of NAPRT in inflammation and signaling was recently discovered and is brought by its extracellular form (eNAPRT)." (PMID 34946971, 2021). "In addition, NAPRT was also reported to be highly expressed in various cancers including ovarian cancer and pancreatic cancer." (PMID 31448236, 2019). "Notably, cancer cells expressing high levels of NAPRT are resistant to NAMPT inhibitors." (PMID 37259338, 2023). "However, PH-dependent cancers with upregulated NAPRT expression are resistant to NAMPT inhibitors." (PMID 38116009, 2023). "To test this hypothesis, we used cancer cells that were either endogenously deficient in functional NAPRT (Namalwa) or that lacked the NAPRT gene by genetic knock-out (Jurkat NAPRT KO and ML2 NAPRT KO)." (PMID 36765744, 2023). "Furthermore, the specificity of our inhibitors was testified by experiments demonstrating that the chemo-sensitizing activity of our inhibitors was abolished upon supplementing cancer cells with sufficient amounts of the substrate (NA) or the downstream product (NAMN) of the NAPRT enzyme." (PMID 35890147, 2022). "Thus, NAPRT could prove beneficial to understanding the function of NAD+ biosynthetic mechanisms in cancer and likely serve as a potential therapeutic target." (PMID 33609766, 2021). "Importantly, D-2HG accumulation and NAPRT hypermethylation that occurs in mutant IDH1/2 cancers could be potential candidates for NAMPT inhibitor trials as they lack NA pathway." (PMID 32111066, 2020).
cancer (continued). "Interestingly, expression of NAPRT, which differs across cancer cell lines, correlates with EMT status, and may be related to the differential effects of NAMPT inhibition on EMT." (PMID 32010616, 2019). "Recent studies have revealed enhancer-driven amplification of nicotinate phosphoribosyltransferase (NAPRT) and the dependency of cancer cells on NAPRT." (PMID 40032852, 2025). "Cancer cells undergoing EMT frequently exhibit alterations in NAD biosynthesis pathways, particularly involving the enzymes NAMPT and NAPRT." (PMID 40282553, 2025). "Cancers are classified into two categories depending on the predominant pathway of NAD+ synthesis: NAPRT- and NAMPT-dependent cancer." (PMID 37175631, 2023). "Patient-derived tumor transcriptomic data and protein levels in various cancer cell lines were analyzed to confirm the correlation between NAPRT depletion and epithelial-to-mesenchymal transition (EMT)-like features in various cancer types." (PMID 37771778, 2023). "In several types of cancer cells, both enzymes are relevant for NAD+ biosynthesis, with NAPRT being responsible for cell resistance to NAMPT inhibition." (PMID 36770640, 2023). "Given the importance of the NAD+ supply in cancer cell survival and the SL relationship between two critical enzymes in NAD+ metabolism, NAMPT and NAPRT, we discovered a novel NAMPT inhibitor with improved biomarker selectivity." (PMID 37771778, 2023). "Recent studies show the relevance of nicotinic acid phosphoribosyltransferase (NAPRT), the rate-limiting enzyme of the Preiss–Handler NAD-production pathway for a large group of human cancers." (PMID 35890147, 2022). "Overall, these findings highlight the specificity of compound 8, since shifting the position of the -OH group from position 4 to position 5 or 6 entirely abolished their ability to sensitize cancer cells to FK866 (and thus, arguably, to inhibit NAPRT)." (PMID 35890147, 2022). "We previously demonstrated that the prototypical NAPRT inhibitor, 2-HNA, synergizes with FK866 in the killing of NAPRT-expressing cancer cells." (PMID 35890147, 2022). "Nicotinate phosphoribosyltransferase (NAPRT) is an enzyme from NAD (Nicotinamide Adenine Dinucleotide) biosynthesis and is mostly studied as a cancer biomarker." (PMID 34946971, 2021). "While normal tissues express NAPRT and can utilize NA to produce NAD, many cancer cells lack the PH pathway for NAD biosynthesis." (PMID 34068917, 2021). "NAPRT, a key enzyme mediating NAD biosynthesis from nicotinic acid, plays an important role in cancer cell metabolism." (PMID 33609766, 2021). "The salvage pathway is important for the maintenance of NAD+ level in cancer cells and involves 2 major enzymes, one of which is phosphoribosyltransferase (NAMPT) and the other is nicotinate phosphoribosyltransferase (NAPRT)." (PMID 33392072, 2020). "Several information about NAPRT expression and regulation emerged in tumors, in relation to the efficacy of NAMPT inhibitors (NAMPTi) as potential anti-cancer agents, as described in the dedicated section NAMPT and NAPRT in Tumors." (PMID 32266141, 2020). "Correlation between NAPRT/NAMPT expression and clinicopathological features in cancer tissues from 261 CRC patients." (PMID 31448236, 2019). "The Preiss-Handler pathway converts nicotinic acid (NA) to NAMN through nicotinate phosphoribosyltransferase (NAPRT), an enzyme that is widely expressed in normal tissues but variably expressed in cancer cells." (PMID 32010616, 2019). "One additional advantage of NMNAT inhibition compared to either NAMPT or NAPRT blockades is that cancer cells would not be able to adapt to NMNAT inhibition through alternative NAD+-producing routes." (PMID 38396769, 2024). "On the other hand, this lack of NAPRT expression is a liability of cancer cells that can also be therapeutically exploited: tumors that lack NAPRT should not be able to utilize NA to replenish their NAD+ content." (PMID 38396769, 2024).
cancer (continued). "Some studies have shown that certain cancers, especially those with BRCAness, can take advantage of niacin by amplifying nicotinic acid phosphoribosyltransferase (NAPRT) and increasing niacin conversion to NAD+, allowing cancer cells to repair their DNA and ensure the progression of tumorigenesis." (PMID 38473246, 2024). "While in tumors, NAMPT is ubiquitously expressed, NAPRT expression levels were found to be largely variable with several cancer cell lines showing either marginal or no NAPRT expression and many other cell lines exhibiting high NAPRT levels." (PMID 38396769, 2024). "This resistance can be reversed through gene silencing or direct inhibition of NAPRT, suggesting that co-administration of NAPRT and NAMPT inhibitors might represent a successful therapy to decrease NAD levels, leading to cancer cell death." (PMID 37259338, 2023). "Failure of NAMPT inactivation is also explained by the presence of alternative sources of NAD+ with the nicotinate phosphoribosyltransferase (NAPRT), which catalyzes the first step of NAD+ biosynthesis from nicotinic acid (the Preiss–Handler pathway), frequently active in cancer cells." (PMID 35681770, 2022). "NAPRT, the rate-limiting enzyme of the Preiss–Handler NAD biosynthetic pathway, has emerged as a key biomarker for the clinical success of NAMPT inhibitors in cancer treatment." (PMID 35890155, 2022). "Studies have shown that the NAPRT gene, the second NAD+ production enzyme, is amplified and overexpressed in cancers, and the combined inhibition of NAMPT and NAPRT may help improve drug resistance in tumors." (PMID 35906622, 2022). "Our study suggests that NAPRT is involved in differentiation and developmental processes and showed that, beyond its application in cancer therapeutic strategies involving NAMPT, NAPRT may participate in the process of carcinogenesis and tumor progression." (PMID 34946971, 2021). "Nevertheless, in light of accumulating evidence that substantiated the significance of NAPRT expression as a parallel regulator of NAD metabolism in cancer and as a biomarker for NAMPT inhibitor therapy, the development of NAPRT inhibitors also represents a promising therapeutic approach." (PMID 34068917, 2021). "In order to select the types of cancer that would better respond to NAMPT inhibition, a determination should be made on whether NAPRT is expressed and functional." (PMID 34946971, 2021). "This conclusion was further substantiated by the observation that neither the overexpression of NAPRT in salvage-dependent cancer cells nor the overexpression of NAMPT in PH-amplified cancer cells has reversed their predestined NAD metabolic pathway." (PMID 34068917, 2021). "From a different angle, it has been recently described in a patent that chemical compounds that inhibit NAPRT activity (including some non-steroidal anti-inflammatory drugs) sensitize cancer cells to NAMPT inhibitors." (PMID 32477131, 2020). "Further support is brought by a patent that discloses chemical compounds that inhibit NAPRT activity (including some non-steroidal anti-inflammatory drugs) and sensitize cancer cells to NAMPT inhibitors." (PMID 32477131, 2020). "Silencing of NAPRT decreases NAD level and increases chemosensitivity of cancer cells." (PMID 31448236, 2019). "NAMPT inhibition is specifically effective in cancer cells in which NAPRT-mediated NAD+ production is not functioning." (PMID 29541451, 2018). "As cancer cells have increased NAD requirements, the main NAD salvage enzymes in humans, nicotinamide phosphoribosyltransferase (NAMPT) and nicotinate phosphoribosyltransferase (NAPRT), are involved in the development of novel anti-cancer therapies." (PMID 26675378, 2016). "In the other cell lines with weak NAPRT expression no methylation was found, strengthening the idea of tissue/cancer type specificity of expression and regulation mechanisms." (PMID 26675378, 2016).
cancer (continued). "To verify whether the A4276's toxicity depends on the perturbation of the NAD+ synthetic pathway, we supplemented NAD+, NAM, and NA with A4276 in NAPRT-negative EMT-cancer cell lines exhibiting sensitivity to A4276, SNU484, and additionally COLO320-HSR." (PMID 37771778, 2023). "The distinct binding mode and inhibition kinetic of A4276 compared to other NAMPT inhibitors may account for the discrepancies mentioned, leading to its higher selectivity against NAPRT-negative cancer cells." (PMID 37771778, 2023). "Cell-based assays clearly demonstrated that our best NAPRT inhibitor, compound 8 (4-hydroxynicotinic acid), but not 5-hydroxy or 6-hydroxynicotinic acid, exhibited marked anti-cancer activity when combined with FK866 while showing no significant growth inhibition when used alone." (PMID 35890147, 2022). "Therefore, targeting NAMPT in tumors lacking NAPRT has been identified as an anti-cancer drug target." (PMID 32111066, 2020). "Therefore, we suppose that co-administration of NAMPT inhibitor and NAPRT inhibitor may effectively decrease NAD levels and kill cancer cells." (PMID 31448236, 2019). "Indeed, cancer cells expressing high levels of NAPRT are resistant to NAMPT inhibitors and both the silencing of the gene and chemical inhibition of the enzyme overcome such resistance, suggesting that the coadministration of NAPRT and NAMPT inhibitors might improve anticancer therapies." (PMID 36770640, 2023). "The molecular mechanisms that dictate the choice of the NAD synthesis pathway (NAPRT and/or NAMPT) in normal or cancer cells is still not clear." (PMID 32477131, 2020). "Moreover, the clear correlation between A4276 cytotoxicity and its response biomarker, NAPRT-deficiency was substantiated by the necessary and sufficient relationship between the NAPRT expression and A4276 resistance in NAPRT positive non-EMT cancer cell lines." (PMID 37771778, 2023).